SSTR2 (somatostatin receptor 2)
Diseases named in the same sentence as SSTR2 in open-access papers (continued):
Sharing a sentence is not in itself a finding about the gene and the disease.
neuroendocrine tumors (continued). "Radiolabelled somatostatin analogues, such as 111In-octreotide, are commonly used in patients for the detection of rare neuroendocrine tumors expressing the human somatostatin receptor type 2 (SSTR2)." (PMID 23762226, 2013). "Recently, standardized uptake values (SUV) with 68Ga-DOTATOC-PET in patients with neuroendocrine tumors have been found to correlate with the expression of the SSTR2 protein by the tumor cells." (PMID 21755051, 2011). "Somatostatin based radiotracers (analogues of somatostatin labelled with radioisotopes) are useful for diagnosis in patients with cancers (Neuroendocrine Tumours-NETs) which express the somatostatin receptor 2 (SSTR2)." (PMID 18928537, 2008). "While this approach has not been translated yet for patient use, targeted radionuclide therapy has been established in clinics using somatostatin analogues such as [177Lu]Lu-DOTATATE (LutatheraTM) for targeting somatostatin receptor-2 (SSTR2)-positive neuroendocrine neoplasms." (PMID 41466165, 2025). "However, in neuroendocrine tumors (NETs), SSTR2 is often significantly overexpressed, making it a highly attractive target for both diagnostic imaging and peptide receptor radionuclide therapy (PRRT) through theranostic approaches." (PMID 39857944, 2025). "Emerging evidence suggests that 212Pb-labeled peptide-based radiopharmaceuticals targeting somatostatin receptor subtype 2 (SSTR2) may provide improved effectiveness compared to beta-particle-based therapies for neuroendocrine tumors (NETs)." (PMID 37955792, 2024). "In addition to NPC, SSTR2 is expressed in other malignancies, including neuroendocrine tumor, thyroid carcinoma, breast cancer, and meningioma, expanding its potential applications in tumor theranostics." (PMID 38176714, 2024). "Consequently, these results present SSTR2 as a promising target for developing innovative therapeutic strategies for treating neuroendocrine tumors." (PMID 39202532, 2024). "In the future, it will be interesting to test whether this inhibitor can boost Sstr2 expression in neuroendocrine tumor models." (PMID 36965619, 2023). "More recently, preliminary data from the DUET-1 phase 1 trial showed that tidutamab (XmAb18087), a BiTE-targeting somatostatin receptor 2 (SSTR2), was well tolerated with a best overall response of stable disease in patients with advanced neuroendocrine tumors." (PMID 36900202, 2023). "In addition, Sstr2 agonist-coupled PET imaging agents and high-energy radionuclides are commonly used as diagnostic and theranostic agents in neuroendocrine tumor patients." (PMID 36965619, 2023). "We therefore tested whether Sstr2 expression in neuroendocrine tumor cells could be enhanced by treatment with small molecule inhibitors of Wnt pathway signaling." (PMID 36965619, 2023). "Peptide receptor radionuclide therapy (PRRT) is an innovative therapeutic option traditionally used as a second-line treatment for advanced (metastatic or inoperable) neuroendocrine tumors (NETs), characterized by the expression of the SSTRs, especially the SSTR2." (PMID 37958702, 2023). "In addition, a radionuclide-coupled Sstr2 agonist was recently approved for use as a tumor cell killing therapeutic in mid-gut neuroendocrine tumors, thus creating a clinical precedent for the conjugation of tumor cell killing analogs to Sstr2 agonists." (PMID 36965619, 2023). "In addition, it was found that PARPi led to enhanced cytotoxic effects of 177Lu-octreotate on both two-dimensional monolayer and three-dimensional spheroid models of neuroendocrine tumor cells expressing SSTR2 and SSTR5." (PMID 38140100, 2023). "Hence, high SSTR2 levels are important for PRRT in neuroendocrine tumors to ensure efficient delivery of radiation." (PMID 36593963, 2023). "However, it is important to note that Sstr2 has been found to colocalize with lysosomes in human neuroendocrine tumors treated with octreotide." (PMID 36965619, 2023).
neuroendocrine tumors (continued). "Importantly, Dvl1-dependent degradation of Sstr2 can be stimulated by overexpression of Wnts and treatment of cells with Wnt pathway inhibitors can boost Sstr2 expression in neuroendocrine tumor cells." (PMID 36965619, 2023). "Unfortunately, not all neuroendocrine tumors express significant levels of Sstr2 and prolonged agonist therapy can cause receptor downregulation." (PMID 36965619, 2023). "Somatostatin receptor 2 (SSTR2) represents a therapeutic target of neuroendocrine tumors." (PMID 36810324, 2023). "As a consequence, the mechanism we have identified here may be frequently operating in human neuroendocrine tumors to regulate Sstr2 expression." (PMID 36965619, 2023). "Among all of the subtypes, SSTR2 was found to be predominantly expressed in neuroendocrine tumors." (PMID 35962347, 2022). "SSTR2 has been shown to be expressed in a subset of neuroendocrine tumors." (PMID 35198446, 2022). "In addition, only 33% of neuroendocrine carcinomas were SSTR2 positive which was significantly lower than in well differentiated neuroendocrine tumors." (PMID 35198446, 2022). "Therefore, further optimization is required to combine an ABD and JR11 to obtain a long-acting SSTR2 antagonist with an adequate biodistribution and pharmacokinetic profile for safe and efficient radionuclide therapy of neuroendocrine tumors." (PMID 36145375, 2022). "In this proof-of-concept study, we further evaluated the potential of high-Am 153Sm for TRNT by radiolabeling to DOTA-TATE, a well-established carrier molecule binding the somatostatin receptor 2 (SSTR2) that is highly expressed in gastroenteropancreatic neuroendocrine tumors." (PMID 36559060, 2022). "SSTR2 has also been recognized as an imaging and treatment target in various neoplasms including neuroendocrine tumors such as paragangliomas and small cell lung carcinomas, but also other malignancies such as thyroid carcinomas, and EBV-driven and non-EBV-driven nasopharyngeal carcinomas." (PMID 35198446, 2022). "However, only since the approval of SSTR2-targeting theranostics following the NETTER-1 trial in neuroendocrine tumours and the positive outcome of the VISION trial has theranostics gained substantial attention beyond nuclear medicine." (PMID 35403861, 2022). "Evidence also suggests that SSTR2 expression may be more common in early than in late tumor stages in neuroendocrine tumors." (PMID 35198446, 2022). "Immunolocalization of somatostatin receptor 2 (SSTR2) could predict the therapeutic efficacy of somatostatin analogues (SSAs) in neuroendocrine tumors (NETs)." (PMID 35159042, 2022). "One large retrospective study of gastroenteropancreatic neuroendocrine neoplasms examined SSTR-2 in 163 patients with high grade gastroenteropancreatic neuroendocrine tumors or cancer of unknown primary." (PMID 34513663, 2021). "Furthermore, a Lu-177-labeled peptide-based radiopharmaceutical (Lu-177-dotatate) targeting somatostatin receptor 2, which is highly expressed in neuroendocrine tumors, was approved by the Food and Drug Administration." (PMID 34638489, 2021). "SSTR2 is a well defined prognostic and therapeutic target for neuroendocrine tumors." (PMID 29467924, 2018). "SSTR2 expression has implications for both imaging and treatment of neuroendocrine tumors." (PMID 28094316, 2017). "Additionally, SSTR2 has been proposed as a therapeutic candidate for neuroendocrine tumors, such as small cell lung cancer." (PMID 29207642, 2017). "Somatostatin analogues, such as octreotide, which display high binding affinity to SSTR2 and lower affinity to SSTR5 and SSTR3 (affinity rank order: SSTR2 > SSTR5 > SSTR3) are efficacious in the treatment of neuroendocrine tumors and exhibit only mild toxicity." (PMID 21985599, 2011).
neuroendocrine tumors (continued). "In this work, we decipher the mechanism of ligand recognition, subtype selectivity and signal bias property of SSTR2 sensing octreotide and paltusotine, which may aid in designing therapeutic drugs with specific pharmacological profiles against neuroendocrine tumors." (PMID 36810324, 2023). "Precious studies demonstrated that SSTR2 might serve as a molecular target in the diagnosis and treatment of thyroid cancer, small intestinal neuroendocrine tumor, and neuroendocrine tumors." (PMID 35281839, 2022). "Like other neuroendocrine tumors, PPGLs are known to express somatostatin receptors (SSTR) especially the SSTR2 subtype; DOTATATE is known to demonstrate higher affinity for SSTR2." (PMID 38625612, 2024). "The expression of the somatostatin receptor 2 gene (SSTR2), which is expressed in other neuroendocrine neoplasms and is therapeutically actionable, has been reported in these tumors." (PMID 39682120, 2024). "177Lu-octreotate increases the activation of poly(ADP-ribose) polymerase-1 (PARP1), a DNA repair enzyme, after internalization in SSTR2-expressing and SSTR5 neuroendocrine tumor cells." (PMID 38140100, 2023). "Both PDX tumors stained positive for the neuroendocrine tumor markers chromogranin A (CgA) and synaptophysin (SYP), but only the NEC913 PDX tumor stained positive for somatostatin receptor 2 (SSTR2)." (PMID 35454817, 2022). "In a study, SSTR2 radiolabeled with Yitrium-90-DOTATOC (90Y-DOTATOC) and Lutetium-177- DOTATATE (177Lu-DOTATATE) was used on neuroendocrine tumors (NETs) as a new radiopharmaceutical therapy." (PMID 36365243, 2022). "Somatostatin receptor 2 (SSTR2) belongs to the GPCR family, and it is overexpressed in the vast majority of neuroendocrine tumors." (PMID 36612012, 2022). "The somatostatin receptor type 2 (SSTR2) is also highly expressed in activated macrophages, especially in M1-like macrophages, and is routinely used for imaging neuroendocrine tumors." (PMID 31281564, 2019). "In one previous study, which investigated the correlation between the expression of SSTR2 and COX-2, the author applied an immunochemistry method to examine the expression of COX-2 and SSTR2 in gastroenteropancreatic neuroendocrine tumors." (PMID 30038293, 2018). "We confirmed substantial SSTR2 expression in both HCC cell lines and patient samples, demonstrating that radiolabeled compounds such as 67Ga-DOTATATE and 177Lu-DOTATATE—widely used for neuroendocrine tumors—can also specifically target HCC." (PMID 39857944, 2025). "While somatostatin can activate five somatostatin receptor subtypes (SSTR1-SSTR5), it has been shown that cyclic octapeptide octreotide selectively binds to the somatostatin subtype-2 (SSTR2) receptor (and, to a lesser extent, SSTR5), which is predominantly expressed in neuroendocrine tumours." (PMID 39451535, 2024). "SSTR2 positive is significantly lower in poorly differentiated than in well-differentiated neuroendocrine neoplasm, whereas 18F-FDG uptake has been proven to be significantly higher in poorly differentiated than in well-differentiated neuroendocrine neoplasm." (PMID 39479016, 2024). "[225Ac]Ac-DOTATATE (RYZ101), an SSTR2 agonist, is currently being evaluated in a phase Ib/III clinical trial in patients with SSTR2-positive gastro-enteropancreatic neuroendocrine tumors that have progressed after treatment with [177Lu]Lu-labeled agonists and compared to SoC (ACTION-1, NCT05477576)." (PMID 39204136, 2024). "Unfortunately, not all neuroendocrine tumors express Sstr2, and Sstr2 expression can be downregulated with prolonged agonist use." (PMID 36965619, 2023). "Finally, both tumor regions exhibited strong membranous reactivity for the G-protein-coupled receptor, somatostatin receptor 2 (SSTR2) in > 50% tumor cells, analogous to score 3 described in neuroendocrine tumors." (PMID 37847488, 2023).
neuroendocrine tumors (continued). "SSTR2-inducing treatments are especially important for neuroendocrine tumor patients not eligible for targeted therapies due to insufficient or undetectable SSTR2 levels." (PMID 36593963, 2023). "If true, this suggests that neuroendocrine tumors that produce one or more RSPOs and Lgr4/5/6 would not downregulate Sstr2 expression, even if they are expressing significant levels of Wnt ligands." (PMID 36965619, 2023). "[177Lu]Lutetium-DOTA-DPhe1, Tyr3-octreotate ([177Lu]Lu-DOTA-TATE), is an analog of somatostatin with high affinity to somatostatin receptor type 2 (SSTR2), which is overexpressed in various neuroendocrine tumors (NETs), including pheochromocytomas/paragangliomas." (PMID 37886645, 2023). "To assess whether Wnts are capable of stimulating endogenous Sstr2 downregulation in neuroendocrine tumor cells, we stably overexpressed Wnt7a in IMR32 cells and then assessed endogenous Sstr2 expression by Western blotting." (PMID 36965619, 2023). "that evaluated a variety of neuroendocrine tumors of the gastrointestinal and pancreatobiliary tract, lung, thyroid, and thymoma and confirmed that the SUV of the 68Ga-DOTATATE scan correlated with the score of SSTR2 expression in the respective tissue." (PMID 35198446, 2022). "For instance, radiolabeled peptides and small molecules have convincingly demonstrated the ability to target the somatostatin receptor subtype-2 (SSTR2) and prostate-specific membrane antigen (PSMA), which are hallmarks of neuroendocrine tumors and prostate cancer, respectively." (PMID 34277418, 2021). "In stark contrast to neuroendocrine tumors, SSTR2 is not highly expressed in GBM, which may limit the success of PRRT with somatostatin analogs." (PMID 40868217, 2025).
meningioma (80 papers, 2009 to 2026). A generally slow growing tumor attached to the dura mater. "Accordingly, a universal targeted therapy such as SSTR2 would provide the advantage of treating virtually the entire cohort of progressive and high-risk meningiomas." (PMID 40149634, 2025). "Some studies reported the uncommon occurrence of SSTR2-positive brain pathology challenging the diagnostic accuracy of [68Ga]Ga-DOTA-SSTR PET for meningiomas." (PMID 35740591, 2022). "SSTR2 is considered a reliable diagnostic biomarker for meningiomas and is the most prevailing SSTRs in human meningiomas." (PMID 34830858, 2021). "Ongoing trials further investigate diagnostic and follow-up imaging feasibility of SSTR2-targeted radiopeptides in meningioma (NCT04298541, NCT03953131)." (PMID 33768405, 2021). "Even though the prognostic value of SSTRs appears to be limited, they can be used as diagnostic markers for meningiomas, especially SSTR2, and can be valuable in any targeted clinical managements." (PMID 34830858, 2021). "Together these data indicate that meningioma spheroids generally retain their key phenotypical features during short-term culturing, but that the culture method does induce progression of grade 1 meningiomas towards a more aggressive phenotype, together with gradual loss of SSTR2 expression." (PMID 39061156, 2024). "Furthermore, the presence of SSTR2 in partially resected meningioma has also been proposed possible cause or risk factor for tumour recurrence." (PMID 38203605, 2023). "The expression of SSTR2 in meningioma might serve as an effective diagnostic and treatment strategies." (PMID 38203605, 2023). "Most of the normal meningeal tissue and all tumor tissues from schwannomas, solitary fibrous tumors/hemangiopericytomas and hemangioblastomas were negative for SSTR2 in our study, supporting the high specificity for SSTR2 as a biomarker for meningiomas in diagnostic routine." (PMID 34830858, 2021). "Furthermore, as merlin is also expressed in some normal neural tissue, meningeal tissue and other brain tumors, the potential use of merlin as a diagnostic marker for meningiomas, like that of epithelial membrane antigen and somatostatin receptor 2, also appears limited." (PMID 40447281, 2025). "SSTR2 is overexpressed in most meningiomas (80%–95% of cases) and is considered a potential target for diagnosis and therapy." (PMID 40774695, 2026). "Somatostatin receptor type 2 (SSTR2) is highly expressed in meningiomas, and SSTR2-targeting radionuclide therapy with [177Lu]Lu-DOTATATE has shown potential activity in the treatment of meningioma in uncontrolled and small studies." (PMID 40774695, 2026). "The use of Gallium-68 (68Ga) - DOTATATE, a contrast agent aimed at SSTR2, had proven valuable in clinical imaging of meningiomas." (PMID 40170861, 2025). "In particular, according to the analyzed literature, in patients with advanced meningiomas that overexpress somatostatin receptor 2, PRRT has been demonstrated to be quite effective and well-tolerated." (PMID 40283171, 2025). "Flow cytometry analysis indicated a binding rate exceeding 98% for the anti-SSTR2 monoclonal antibody with meningioma CH157-MN cells, while remaining below 5% in normal arachnoid AC07 cells." (PMID 40170861, 2025). "Somatostatin analogs carrying high affinity to SSTR2, are an attractive treatment option for meningiomas and maintain a targeted yet generalizable and scalable approach to treatment." (PMID 40149634, 2025). "Somatostatin Receptor 2 (SSTR2) is typically overexpressed in meningiomas and serves as a marker for meningothelial cells." (PMID 39941893, 2025). "Human meningioma expresses SSTR2 although the correlation between SSTR2 expression and histological grade or subtype is still debated." (PMID 39969014, 2025). "Given the high expression of somatostatin receptors (SSTR) in meningiomas, specifically the SSTR2a subtype found in 90% of cases, SSTR2 emerges as an ideal target for meningioma therapy." (PMID 40170861, 2025).